TLR3 (toll like receptor 3)
Diseases named in the same sentence as TLR3 in open-access papers (continued):
Sharing a sentence is not in itself a finding about the gene and the disease.
COVID-19 (continued). "TLR3 mRNA mean expression in polymorphonuclear and mononuclear cells in the COVID-19 MILD group was 2.06 and 1.94, respectively (p 0.945)." (PMID 34315957, 2021). "Top genes include IL1A15 and other components of the innate and adaptive immune systems (such as CXCL10, CD4 and TLR3), which have previously been shown to contribute to COVID-19 pathogenesis." (PMID 33339864, 2020). "TLR-2, TLR-3, and TLR-4 activation by COVID-19 causes the release of inflammatory cytokines such as IL-1β." (PMID 33082858, 2020). "Twenty-nine model complexes of TLR3 and COVID-19 vaccine were determined, from which just one complex with the lower binding energy score of −1156.2 was selected to show." (PMID 32849643, 2020). "A recent study identified the loss-of-function mutation at the loci of TLR3 and IRF7 in severe patients with influenza and COVID-19, resulting in preventing type 1 IFN production, thus emphasizing the significance of type 1 IFN in controlling virus production." (PMID 33362771, 2020). "Indeed, the association of the heterozygous missense TLR3 variant, the homozygous CCR5Δ32 deletion, and the production of anti-IFN type I antibodies likely contributed to the severe course of COVID-19 and WNV infection in this patient." (PMID 38976510, 2025). "Animal experiments have shown that COVID-19 mice lacking the TLR3/TLR4 adapter TRIF are more susceptible and have a higher risk of death, suggesting that the TLRs signaling pathway is critical for antiviral resistance." (PMID 40584714, 2025). "For example, TLR3 hyperactivation can lead to a cytokine storm and the subsequent severe COVID-19." (PMID 38240884, 2024). "The analysis identified enrichment for rare variants in 13 gene loci involved in TLR3- and IRF7-dependent immunity, with experimental validation including evidence for a role for autosomal recessive AR deficiencies of IRF7 and IFNAR1 in severe COVID-19." (PMID 38549844, 2024). "Given the protective role of TLR3 and its function in innate immunity during SARS-CoV-2 infection, other potentially deleterious variants could similarly influence COVID-19 clinical outcomes." (PMID 38605121, 2024). "Several TLRs, such as TLR2, TLR3, TLR4 and TLR7, have been associated with COVID-19 severity." (PMID 37175768, 2023). "The clinical outcomes in individuals infected by SARS-CoV-2 range from no symptoms to severe or lethal COVID-19, and single-gene inborn errors of the TLR3 pathway have been found to be risk factors for this disease." (PMID 37158982, 2023). "Therefore, SNPs rs3775291 and rs3775290 of the TLR3 gene were genotyped in this cohort and their frequencies compared between the study groups for symptomatology and severity of COVID-19." (PMID 38173795, 2023). "Recent studies demonstrated that mutations of TLR3 and TLR7 and some of the downstream signaling molecules required for type I IFNs production are correlated with the severity of COVID-19, indicating the critical roles of TLR3 and TLR7 signaling in the control of SARS-CoV-2." (PMID 37158982, 2023). "Our predictive models using the combination of Charlson Comorbidity Index, sex, procalcitonin, systemic TLR3 expression and IL-6 and IL-8 in BAL were able to describe a broad range of clinically relevant outcomes in patients with severe COVID-19-associated ARDS." (PMID 36631778, 2023). "Therefore, PRL and TLR3 were established as the two key RNAs related to the prognosis of COVID-19 patients." (PMID 37966347, 2023). "Overall, severe COVID-19 might be characterized by dysregulation in IFNγ, IFNλ and TLR3, 7 and 8 production." (PMID 36985262, 2023). "Indeed, L. rhamnosus increases expression of TLR3, which targets double-stranded viral DNA and only appears in COVID-19 patients once the virus has replicated." (PMID 37513775, 2023).
COVID-19 (continued). "Although these data are limited, in aggregate they suggest that the various forms of AM all share the characteristic of activating both virus-associated (TLR3, TLR7, TLR8 or TLR9) and bacteria-associated (TLR2 and TLR4) innate receptors with severe COVID-19, KD and MIS-C." (PMID 36769320, 2023). "TLR2, TLR3, TLR4 and TLR7 have been associated with COVID-19 severity." (PMID 37175768, 2023). "Inhibition of TLR3 by famotidine decreases IL-6 and reduces the risk of intubation and death in patients hospitalized with COVID-19 and alleviates symptoms in non-hospitalized patients with COVID-19." (PMID 35356515, 2022). "Illustratively, in two patients with IFN-I deficiency (autosomal dominant TLR3 and IRF3 deficiency) who developed severe COVID-19, it was shown that treatment with a single dose of recombinant IFNα2a could resolve symptoms within 48 h." (PMID 35986347, 2022). "In this report, we demonstrate that COVID-19 plasma exosomes stimulate protein expression of TLR3 as well as TLR7 and TLR9 in CD4+ T cells, CD8+ T cells, and CD14+ monocytes compared with cells that remained untreated, treated with plasma exosomes from non-COVID-19 or healthy donors, or poly(I:C)." (PMID 36526691, 2022). "In another work, TLR-3, IRF3, and IRF7 variants were detected in patients with severe COVID-19." (PMID 35062298, 2022). "In mDCs, we found TLR3 viral RNA sensing pathways were downmodulated in all COVID-19 subgroups." (PMID 36439166, 2022). "Additionally, a clinical study to evaluate the inhibition of TLR3-mediated inflammatory responses by Famotidine to improve outcomes in patients with COVID-19 has been conducted (NCT04389567, NCT04504240, NCT04724720, NCT04370262)." (PMID 34834939, 2021). "Zhang and colleagues considered that similar variants in TLR3 and IFN production or response may underlie susceptibility to lethal coronavirus disease 2019 (COVID-19)." (PMID 34199501, 2021). "Hence, an investigation of TLR3 expression among mononuclear and polymorphonuclear cells in the peripheral blood of COVID-19 patients was performed." (PMID 34315957, 2021). "Other possible DAMPs that may be playing roles in COVID-19 include extracellular RNAs that can activate TLR3 and TLR7, as well as extracellular hemoglobin, which activates NLRP3 and is associated with coagulation dysregulation and microclotting." (PMID 33672738, 2021). "Two functionally similar but mechanistically independent mechanisms related to the type I IFN response, i.e. neutralizing autoantibodies against type I IFNs and inborn errors of TLR3- and IRF7-dependent type I IFN immunity, have been demonstrated to be associated with severe COVID-19." (PMID 34531865, 2021). "The COVID-19 patient–derived EVs-induced NETs formation was suppressed completely in the presence of the vacuolar type H+-ATPase inhibitor bafilomycin A1 (BafA1, 100 nM), suggesting that endolysosomal TLRs such as TLR3, TLR7, TLR8 and TLR9 mediate NETs formation." (PMID 37904132, 2023). "Therefore, it is likely that ORF3a-induced IL-6 and TNF-α production through NF-κB, TLR3 or TLR4 could all contribute to the severity of COVID-19." (PMID 35356515, 2022). "In addition, COVID-19 plasma exosomes stimulated expression of TLR3, TLR7, TLR8, and TLR9 by PBMC." (PMID 36526691, 2022). "In addition, GRP78 has been identified as a DAMP for specific TLRs (TLR2 and TLR3) and may account for promotion of augmented inflammation in COVID-19 patients." (PMID 33498183, 2021). "Consequently, the lower TLR3 expression in the COVID-19 SEVERE group could reflect a diminished fraction of lymphocytes in their peripheral blood samples." (PMID 34315957, 2021). "It has been found that about 3.5% of COVID-19 patients had known autosomal-recessive (AR) deficiencies [interferon regulatory factor 7 (IRF7) and IFNAR1] and autosomal-dominant deficiencies (AD) [toll-like receptor 3 (TLR3), UNC93B1, TICAM1, TBK1, IRF3, IRF7, IFNAR1, and IFNAR2]." (PMID 34335535, 2021).
COVID-19 (continued). "Finally, also, the increased expression of TLR3 might be positively translated into the COVID-19 context: indeed, it has been previously reported that its overexpression protects neutropenic mice from meningoencephalitis." (PMID 33014780, 2020). "TLR3 (p < 0.001), TLR7 (p < 0.001), and TLR8 (p < 0.001) expression levels were considerably greater in COVID-19 patients compared to the control group." (PMID 38868379, 2024). "Genes impacting mitochondrial function include 31 of 37 in mitochondrial DNA and nuclear genes encoding mitochondrial proteins, including ten EDS-related (NDUFA-11/S3, OPA1, TYMP, etc.)and three COVID-19-related (STAT2, TLR3, NDUFAF7) genes." (PMID 37504295, 2023). "Therefore, the comparative analysis of the presence of missense SNPs rs3775291 (C>T) and rs3775290 (C>T) of TLR3 gene, with already proven roles in reducing the performance of this immune receptor, are of great immunogenetic interest for evaluating interventional health measures against COVID-19." (PMID 38173795, 2023). "A strategic immuno-evasive strategy employed by COVID-19, which successfully reduces host immunity, is through blocking viral-specific TLRs such as TLR7 and TLR3." (PMID 37513775, 2023). "Studies of innate activation unrelated to COVID-19 are also very limited, revealing TLR1, TLR2, TLR3, TLR4, TLR7 and TLR8 activation." (PMID 36769320, 2023). "Given that mature neutrophils express all TLRs except TLR3, we analyzed the expressions of TLR7, TLR8 and TLR9 in normal human neutrophils after being treated with EVs from COVID-19 patients (n = 6) and HC subjects (n = 6), respectively." (PMID 37904132, 2023). "In the present study, we identified high PRL/TLR3 and low PRL/TLR3 endotypes of COVID-19 patients in two heterogeneous cohorts using whole-blood samples of the patients at the time of admission to the ICU." (PMID 37966347, 2023). "A significant positive correlation was observed between CRP and mRNA expression of TLR3 (rho = 0.85, P = 0.001), TLR7 (rho = 0.80, P = 0.004), TLR8 (rho = 0.78, P = 0.010), and TLR9 (rho = 0.48, P = 0.035) in the all COVID-19 cases." (PMID 35538443, 2022). "It was seen that the transcript levels of TLR3, TLR7, TLR8, and TLR9 were overexpressed in the COVID-19 patients with clinical symptoms needing hospitalization as well as in those with clinical symptoms without needing for hospitalization compared to controls." (PMID 35538443, 2022). "There was a significant positive correlation between LDH level and mRNA expression of TLR3 (rho = 0.39, P = 0.041), TLR7 (rho = 0.41, P = 0.008), and TLR8 (rho = 0.49, P = 0.030) in the whole COVID-19 cases." (PMID 35538443, 2022). "There was a significant upregulation of mRNA of TLR3 (fold change = 2.4, P = 0.017), TLR7 (fold change = 2.0, P = 0.009), TLR8 (fold change = 2.2, P = 0.004), and TLR9 (fold change = 2.9, P = 0.010) in COVID-19-Group B compared with the Control-Group III." (PMID 35538443, 2022). "The network pharmacology showed CHM formulas affected several inflammation-related proteins for COVID-19, including IL-10, TNF-α, IL-6, TLR3, and IL-8, in which Dexamethasone and Aspirin covered only IL-10 and TNF-α." (PMID 35890093, 2022). "More specifically, TLR3, TLR7, TLR8, and TLR9 were upregulated in the COVID-19 cases with clinical symptoms and needing hospitalization as well as in those with clinical symptoms but without requirement for hospitalization for supportive cares." (PMID 35538443, 2022). "There was positive significant correlation between Neutrophil–lymphocyte ratio and mRNA expression of TLR3 (rho = 0.62, P = 0.012), TLR7 (rho = 0.60, P = 0.013), TLR8 (rho = 0.49, P = 0.011), and TLR9 (rho = 0.39, P = 0.036) in all COVID-19 cases." (PMID 35538443, 2022). "There was a significant upregulation of mRNA of TLR3 (fold change = 2.1, P = 0.022), TLR7 (fold change = 1.9, P = 0.025), TLR8 (fold change = 2.0, P = 0.039), and TLR9 (fold change = 2.9, P = 0.024) in COVID-19-Group B compared with the Control-Group I." (PMID 35538443, 2022).
COVID-19 (continued). "There was a significant upregulation of mRNA of TLR3 (fold change = 2.9, P = 0.011), TLR7 (fold change = 2.2, P = 0.020), TLR8 (fold change = 2.9, P = 0.040), and TLR9 (fold change = 2.5, P = 0.001) in COVID-19-Group A in comparison to the Control-Group II." (PMID 35538443, 2022). "In conclusion, our investigation indicated that the mRNA expressions of TLR3, TLR7, TLR8, and TLR9 are upregulated in the nasopharyngeal epithelial cells from COVID-19 patients." (PMID 35538443, 2022). "There was positive significant correlation between ESR and mRNA expression of TLR3 (rho = 0.71, P = 0.005), TLR7 (rho = 0.62, P = 0.011), TLR8 (rho = 0.65, P = 0.029), and TLR9 (rho = 0.40, P = 0.044) in all COVID-19 cases." (PMID 35538443, 2022). "In addition, mutations in TLR3 and TLR7 might be playing a role in SARS-Co-V-2 disease outcomes: in-born errors in TLR3 and IRF7 were associated with disease severity and mortality in COVID-19 patients." (PMID 35336937, 2022). "Further studies are needed to define the role of TLR3 in SARS-CoV-2 infection and the development of COVID-19." (PMID 36419185, 2022). "When compared to the COVID-19 MILD group, the COVID-19 SEVERE group had lower expression of TLR3 and overexpression of TLR4." (PMID 34315957, 2021). "On the other hand, TLR3 mRNA was decreased, while TLR4 mRNA was increased in the COVID-19 SEVERE group when compared to the COVID-19 MILD group." (PMID 34315957, 2021). "They revealed how inborn errors at the 13 human loci, which are known to govern TLR3- and IRF7-dependent type I IFN immunity, can lead to life-threatening pneumonia in COVID-19 patients." (PMID 34976886, 2021). "In a separate set of patients (COVID-19 MILD N = 10; COVID-19 SEVERE N = 10), differences in TLR3 expression between distinct cell types were investigated." (PMID 34315957, 2021). "Importantly, both TLR3 and TLR4 are known to recognize RNA viruses and trigger NF-kB-mediated proinflammatory responses, contributing to the severity of COVID-19 (59, –, 61)." (PMID 38078754, 2024). "As would be expected from the SARS-CoV-2 viral activation pattern just described, TLR3, TLR7, TLR8, TLR9, NLRP3, RIG-1 and MDA-5 are activated in patients with severe COVID-19." (PMID 36769320, 2023). "We previously reported that impaired type I IFN activity, due to inborn errors of TLR3- and TLR7-dependent type I interferon (IFN) immunity or to autoantibodies against type I IFN, account for 15–20% of cases of life-threatening COVID-19 in unvaccinated patients." (PMID 37020259, 2023). "There was a significant positive correlation between percentage of oxygen saturation and transcript levels of TLR3 (rho = 0.37, P = 0.041), TLR7 (rho = 0.30, P = 0.026), TLR8 (rho = 0.35, P = 0.022), and TLR9 (rho = 0.39, P = 0.028) in the overall COVID-19 cases." (PMID 35538443, 2022). "Modulation of TLR3, TLR7, TLR8, TLR9 in the epithelial cells of COVID-19 cases may estimate the disease severity and requirement for hospitalization." (PMID 35538443, 2022). "Therefore, the analysis of the genotypes of TLR2, TLR3, TLR4, TLR6, TLR7, TLR8, and TLR9 is important for the study of COVID-19." (PMID 35327350, 2022). "In addition, a significant positive correlation was detected between WBC count and transcript levels of TLR3 (rho = 0.55, P = 0.020), TLR7 (rho = 0.59, P = 0.029), TLR8 (rho = 0.44, P = 0.012), and TLR9 (rho = 0.41, P = 0.034) in the whole COVID-19 cases." (PMID 35538443, 2022). "The IEI affecting the TLR3- and TLR7-signalling pathways established so far could already explain up to 5% of critical COVID-19 cases in men under the age of 60 years." (PMID 35986347, 2022). "A pharmacological inhibitor of TLR3 considerably reduced cytokine and chemokine production by CD4+ and CD8+ T cells but not by CD14+ monocytes, highlighting divergent signaling pathways of immune cells in response to COVID-19 plasma exosomes." (PMID 36526691, 2022).
COVID-19 (continued). "It was observed that oxygen saturation, WBC count, Neutrophil–lymphocyte ratio, LDH level, CRP level, and ESR level had a significant positive correlation with the transcript levels of TLR3, TLR7, TLR8, and TLR9 in the COVID-19 Group A as well as COVID-19 Group B patients." (PMID 35538443, 2022). "Both TLR3 and TLR4-mediated pro-inflammatory responses contribute to the severity of COVID-19." (PMID 35356515, 2022). "A specific dsRNA/TLR3 inhibitor blocked the expression of cytokines by T lymphocytes, but not by monocytes, in response to COVID-19 plasma exosomes." (PMID 36526691, 2022). "Taking COVID-19 as an example, it has been under argument whether the initial type I IFN responses mediated by TLR3 are sufficiently involved in the onset and aggravation of COVID-19 or not." (PMID 35281442, 2022). "The mRNA expression of TLR3 (fold change = 3.4, P = 0.032), TLR7 (fold change = 2.0, P = 0.041), TLR8 (fold change = 2.8, P = 0.019), and TLR9 (fold change = 2.1, P = 0.016) was significantly upregulated in COVID-19- Group A compared with the Control-Group I." (PMID 35538443, 2022). "Contrary to TLR3, the mRNA transcription for TLR4 was higher in the COVID-19 SEVERE group." (PMID 34315957, 2021). "As TLR3 is a major producer of type I and III IFNs, activating TLR3 and restoring IFN concentrations during SARS-CoV-2 could be a viable treatment for COVID-19 patients." (PMID 33498183, 2021). "Furthermore, TLR3 and TLR4 are specifically related by different studies as part of immune response in COVID-19 (Patra, Chandra Das & Mukherjee, 2021; Khanmohammadi & Rezaei, 2021; Kaushik, Bhandari & Kuhad, 2021)." (PMID 34909278, 2021). "TLR3 mRNA mean expression in polymorphonuclear and mononuclear cells in the COVID-19 SEVERE group was 1.82 and 1.77 respectively (p 0.931).TLR3 mRNA mean expression in polymorphonuclear was 2.06 in the MILD group and 1.82 in the SEVERE group however not statistically significant (p 0.821)." (PMID 34315957, 2021). "In particular, severe COVID-19 patients (as well as influenza-associated ALI/ARDS) are characterized by the activation and increased expression of TLR3 and TLR7—two virus-activated receptors—while NOD2 does not appear to play a major role." (PMID 33672738, 2021). "The role of TLR3 and TLR7 in the pathogenesis of COVID-19 is discussed in the study by Sallenave." (PMID 32604797, 2020). "Potential explanations could be a discrepancy between mRNA and protein expression and TLR3 induction in the lung that was not sufficient for local virus control -hence the complicated COVID-19 course- but strong enough for systemic containment of disease." (PMID 36631778, 2023). "MicroBeads selected CD4+ T cells, CD8+ T cells, and CD14+ monocytes from PBMCs were treated with plasma exosomes from early-stage COVID-19 patients and non-COVID donors for 16 h at 37 °C, followed by flow cytometry for expression of TLR3, TLR7, TLR8, and TLR9 gating on live cells." (PMID 36526691, 2022). "It was seen that mRNA expression of TLR3 (fold change = 2.2, P = 0.004), TLR7 (fold change = 2.5, P = 0.038), TLR8 (fold change = 3.1, P = 0.018), and TLR9 (fold change = 3.0, P = 0.026) was significantly upregulated in the COVID-19- Group A in comparison to Control-Group III." (PMID 35538443, 2022). "Here in the current investigation, we attempted to measure the mRNA expression levels of TLR3, TLR7, TLR8, and TLR9 in the nasopharyngeal epithelial cells from COVID-19 patients in order to determine the role of these innate immune system molecules in the inflammatory settings of COVID-19 patients." (PMID 35538443, 2022). "It was observed that mRNA expression of TLR3 (fold change = 2.3, P = 0.016), TLR7 (fold change = 2.1, P = 0.033), TLR8 (fold change = 2.3, P = 0.022), and TLR9 (fold change = 2.4, P = 0.019) was significantly upregulated in the COVID-19- Group B versus Control-Group II." (PMID 35538443, 2022).